B3GNT7 (UDP-GlcNAc:betaGal beta-1,3-N-acetylglucosaminyltransferase 7)
Description:
N-acetyl glucosamine (GlcNAc) transferase that catalyzes the transfer of GlcNAc via a beta1->3 linkage from UDP-GlcNAc to the non-reducing terminal galactose (Gal) in the linearly growing chain of N- and O-linked keratan sulfate proteoglycans. Cooperates with B4GALT4 galactosyltransferase and CHST6 and CHST1 sulfotransferases to construct and elongate mono- and disulfated disaccharide units [->3Galbeta1->4(6-sulfoGlcNAcbeta)1->] and [->3(6-sulfoGalbeta)1->4(6-sulfoGlcNAcbeta)1->] within keratan sulfate polymer. Involved in biosynthesis of N-linked keratan sulfate proteoglycans in cornea, with an impact on proteoglycan fibril organization and corneal transparency (By similarity). May play a role in the maintenance of tissue architecture by suppressing cellular motility and invasion (By similarity).
Synonyms: beta3GnT7
Tractability: Antibody: UniProt predicts a signal peptide or a membrane-spanning region.
Gene: Protein-coding gene on chromosome 2 (231,395,671 to 231,408,799, forward strand). Ensembl gene ENSG00000156966.
Subcellular location: Golgi apparatus membrane
Subcellular location (Human Protein Atlas): Golgi apparatus; Cytosol; Mitotic spindle
Pathways (Reactome):
Metabolism: Keratan sulfate biosynthesis
Metabolism of proteins: O-linked glycosylation of mucins
Gene Ontology:
Molecular function: acetylglucosaminyltransferase activity; N-acetyllactosaminide beta-1,3-N-acetylglucosaminyltransferase activity; protein binding; UDP-glycosyltransferase activity; hexosyltransferase activity
Biological process: keratan sulfate proteoglycan biosynthetic process; glycoprotein biosynthetic process
Cellular component: Golgi membrane; membrane
Genetic constraint (gnomAD): Loss-of-function variants: 9 observed, 4.27 expected, observed/expected ratio (o/e) 2.11. That is too few expected variants to judge how well the gene tolerates losing a copy. Missense variants: 463 observed, 559.25 expected, observed/expected ratio (o/e) 0.83, 90% interval 0.77 to 0.89. Synonymous variants: 252 observed, 248.1 expected, observed/expected ratio (o/e) 1.02, 90% interval 0.92 to 1.13.
Homologues: Orthologues: chimpanzee B3GNT7 (99% identical), macaque B3GNT7 (96% identical), pig B3GNT7 (89% identical), rabbit B3GNT7 (89% identical), dog B3GNT7 (88% identical), guinea pig B3GNT7 (86% identical), mouse B3gnt7 (85% identical), rat B3gnt7 (85% identical), tropical clawed frog b3gnt7 (60% identical), zebrafish b3gnt7 (55% identical), Drosophila melanogaster brn (24% identical), Caenorhabditis elegans bre-5 (19% identical), and 2 more. Paralogues in human: B3GNT9 (40% identical), B3GNT4 (37% identical), B3GNT6 (36% identical), B3GNT3 (35% identical), B3GNT2 (33% identical), B3GNT8 (28% identical), B3GNT5 (26% identical), B3GALT2 (26% identical), B3GALT4 (22% identical), B3GALT5 (21% identical), B3GALNT1 (21% identical), B3GALT9 (20% identical), and 3 more.
Diseases named in the same sentence as B3GNT7 in open-access papers:
B3GNT7 is named in the same sentence as 13 diseases in open-access papers, as found by Europe PMC text mining. Sharing a sentence is not in itself a finding about the gene and the disease. The quoted sentences say what the papers report.
colitis (4 papers, 2022 to 2026). Inflammation of the colon. "Intestinal B3GNT7 deficiency increases susceptibility to colitis and enteric infection in mice, showing that B3GNT7-dependent glycosylation confers protective properties to colonic mucus." (PMID 42239473, 2026). "Our study has elucidated a significant role for B3GNT7 in the inflammatory response associated with colitis." (PMID 38886669, 2024). "As advancements in the comprehension of colitis pathogenesis mechanisms have been achieved in recent years, there has been a burgeoning interest among researchers in the role of B3GNT7 in intestinal epithelial homeostasis." (PMID 38886669, 2024). "Third, experimental studies utilizing animal models and clinical specimens are essential to corroborate the functions and mechanisms of B3GNT7, thereby further affirming its significant role in colitis." (PMID 38886669, 2024). "Delineating the role of B3GNT7 in colitis facilitates a deeper understanding of the disease’s pathophysiological underpinnings and lays the groundwork for the investigation of novel therapeutic approaches." (PMID 38886669, 2024). "Intriguingly, reduced expression of OXTR and B3GNT7 is observed in patients with colitis and CAC, underscoring the clinical relevance of our findings." (PMID 38979515, 2024). "Emerging evidence indicates that B3GNT7 is pivotal in modulating the intestinal mucosal barrier, a key determinant in the onset and progression of colitis." (PMID 38886669, 2024). "The DSS-induced colitis model was successfully established, and transcriptomic analysis identified a marked downregulation of B3GNT7 expression in the colonic tissues compared to the controls." (PMID 38886669, 2024). "An experimental colitis model was induced using DSS in mice to investigate B3GNT7 expression in the colon via transcriptomics and immunohistochemistry." (PMID 38886669, 2024). "The aberrant expression and glycosylation modifications of the mucin family in the context of colitis suggest that B3GNT7 may interact with mucins secreted by goblet cells and contribute to the restoration of intestinal barrier function." (PMID 38886669, 2024). "The downregulation of B3GNT7 expression in the colonic tissues of UC patients may contribute to the compromised mucin barrier function and the exacerbation of colitis." (PMID 38886669, 2024). "Our study found that the downregulation of B3GNT7 expression in the colonic tissues of UC patients may contribute to the compromised mucin barrier function and the exacerbation of colitis." (PMID 38886669, 2024). "Furthermore, downregulation of b3gnt7 gene expression was observed during dextran sodium sulfate (DSS)-induced colitis in mice." (PMID 34864058, 2022). "Consequently, it is plausible to suggest that dysregulated expression of B3GNT7 may result in immune dysfunctions, triggering or exacerbating the onset of colitis." (PMID 38886669, 2024). "Additionally, B3GNT7 is intricately involved in immune regulation within the context of colitis." (PMID 38886669, 2024). "Finally, the exploration of therapeutic interventions aimed at modulating B3GNT7, such as its activation or inhibition, could potentially ameliorate the pathological progression of colitis." (PMID 38886669, 2024). "To understand the relevance of the decreased expression of OXTR and B3GNT7 in humans, we analyzed an independent cohort of patients with UC and found decreased expression of OXTR in colitis." (PMID 38979515, 2024).
colon cancer (3 papers, 2017 to 2024). "Notably, downregulation of B3GNT7 gene expression has been linked to enhanced metastatic potential of colonic cancer cells." (PMID 34864058, 2022). "It has been reported that B3GNT7 is abundantly expressed in normal colon cells and significantly suppressed in colon cancer tissues by epigenetic alterations with effects on the metastatic spread potential." (PMID 28376875, 2017). "B3GNT7, which is involved in the combination of poly-N-acetyllactosamine chains and triggers α1-3-fucosylation of glycoproteins in IECs, has been exhibited to inhibit the metastasis of colon cancer cells." (PMID 38979515, 2024).
colorectal cancer (1 paper, 2024). A primary or metastatic malignant neoplasm that affects the colon or rectum. "Conversely, B3GNT7 and GAL3ST2 were downregulated and were protective factors in colorectal cancer." (PMID 39309424, 2024).
glioma (1 paper, 2022). A benign or malignant brain and spinal cord tumor that arises from glial cells (astrocytes, oligodendrocytes, ependymal cells). "The top were GALNT3, ALG6 and B3GNT7, which displayed a p < 1 × 10−9 in the low-grade glioma (LGG) cohort." (PMID 35565254, 2022).
hyperreactivity (1 paper, 2023). "TRPM4 is associated with cold airway hyperreactivity, TMEM102 and CD200R1 are involved in Th cell activation, and ST3GAL3 and B3GNT7 are associated with protecting the distal airways against destruction." (PMID 38203236, 2023).
liver cancer (1 paper, 2024). An epithelial or non-epithelial malignant neoplasm that arises from the liver. "Few studies have explored the function of B3GNT7 in liver cancer and immune cells." (PMID 38604154, 2024).
Obesity (1 paper, 2018). Accumulation of substantial excess body fat. "Among the genes affiliated with the 119 significant CpGs, SOCS3 and DOK2 were differentially expressed in the SAT of obesity patients, while seven genes (SOCS3, PRR5L, ABCG1, BRDT, B3GNT7, ZNF710, and RARRES1) were differentially expressed in the VAT of obesity patients." (PMID 30619480, 2018).
cancer (6 papers, 2019 to 2025). A tumor composed of atypical neoplastic, often pleomorphic cells that invade other tissues. "Specifically, related to this pathway, we observed down-regulation of genes such as b4galt3, st3gal1, and a notable 5-fold increase in b3gnt7 expression, a combination that is consistent with current metastasis literature in many cancer types." (PMID 40719625, 2025). "The network surrounding Il10ra shows that many of them are cancer related, e.g., Reg3g, Aoc1, Mep1a, Irf7, Gas6, B3gnt7, Tap1, Tgm2, and Nos2." (PMID 33396408, 2020). "B3GNT2/5 genes encoding β3GnT enzyme, one of the critical glycosyltransferases involved in this process has been shown to be associated with cancer cell migration, invasion, and metastasis in cancers, however, β3GnT7 enzyme decreases cancer cell motility and invasion." (PMID 31273306, 2019). "This showed that B3GNT7 might be a pro-cancer progression gene." (PMID 38604154, 2024). "B3GNT7, TIAM2 and TMPRSS3 were all found to promote the proliferation, invasion and migration of cancer cells." (PMID 32385351, 2020). "We found lots of them might play a key role in the transformation of enterocyte progenitor cells to cancer cells such as MALAT1, B2M, EEF1A1, RPL5, B3GNT7, RHOB and ACTB might play a key role in the transformation of enterocyte progenitor cells to cancer cells." (PMID 36944972, 2023).
tumor (1 paper, 2019). "We anticipated that increased B3GNT7 gene expression in liver metastasis compared to either primary tumor or lung metastatic tissues could be caused by either epigenetic or altered transcriptional regulatory mechanisms." (PMID 31273306, 2019). "In contrast, B3GNT7 gene expression remains constant between primary tumor and lung metastasis and is increased in liver metastasis." (PMID 31273306, 2019). "Of the different genes encoding β3GnT enzyme, we examined the expression of B3GNT1-2 and B3GNT7 genes which showed an increase and decrease expressions, respectively, in lung metastatic tissues compared to primary tumor tissues." (PMID 31273306, 2019).
B3GNT7 also shares sentences with these, for which no sentence is quoted: immune dysfunctions (1 paper); infection (1); lymph node metastasis (1); thyroid cancer (1).